GYPB (glycophorin B (MNS blood group))
Description:
Component of the ankyrin-1 complex, a multiprotein complex involved in the stability and shape of the erythrocyte membrane.
Synonyms: CD235b; GPB; SS; PAS-3; GYP; MNS
Tractability: Small molecule: a structure with a bound ligand is known. Antibody: its Gene Ontology location is reachable by antibodies, with high confidence; UniProt places it where antibodies can reach, with medium confidence; UniProt predicts a signal peptide or a membrane-spanning region.
Gene: Protein-coding gene on chromosome 4 (143,996,104 to 144,019,380, reverse strand). Ensembl gene ENSG00000250361.
Subcellular location: Cell membrane
Pathways (Reactome):
Hemostasis: Cell surface interactions at the vascular wall
Gene Ontology:
Molecular function: protein binding
Cellular component: ankyrin-1 complex; plasma membrane; membrane
Genetic constraint (gnomAD): Loss-of-function variants: 7 observed, 7.41 expected, observed/expected ratio (o/e) 0.94, 90% interval 0.53 to 1.69. That is too few expected variants to judge how well the gene tolerates losing a copy. Missense variants: 39 observed, 47.58 expected, observed/expected ratio (o/e) 0.82, 90% interval 0.63 to 1.07. Synonymous variants: 13 observed, 17.75 expected, observed/expected ratio (o/e) 0.73, 90% interval 0.48 to 1.16.
Homologues: Orthologues: macaque GYPA (68% identical), dog GYPA (44% identical), mouse Gypa (32% identical). Paralogues in human: GYPA (81% identical), GYPE (58% identical).
Diseases named in the same sentence as GYPB in open-access papers:
GYPB is named in the same sentence as 13 diseases in open-access papers, as found by Europe PMC text mining. Sharing a sentence is not in itself a finding about the gene and the disease. The quoted sentences say what the papers report.
malaria (23 papers, 2010 to 2025). Malaria is a serious and sometimes fatal disease caused by a parasite that commonly infects a certain type of mosquito which feeds on humans. "These assays will enable better identification of GYPB deletions for large genetic association studies and functional experiments to understand the role of this gene cluster region in susceptibility to malaria and other diseases." (PMID 33325748, 2021). "A particular complex structural variant, called DUP4, creates a GYPB-GYPA fusion gene known to confer resistance to malaria." (PMID 32600246, 2020). "GYPA and GYPB are associated with human malaria and serve as invasion receptors for the malaria parasite in red blood cells, and their structural variations play a significant role in natural resistance to malaria." (PMID 39336704, 2024). "Developing less expensive high throughput assays targeting the less common GYP variants will provide a better understanding of the distribution and functional effects of these variants on susceptibility and pathogenesis of malaria and other disease causing pathogens that also use GYPB as a receptor." (PMID 33325748, 2021). "However, six of the nine RBC invasion receptors contained variants associated with growth, including a SNP in glycophorin B (GYPB) that has been linked to malaria risk in Brazil." (PMID 34553687, 2021). "Furthermore, rs186873296 FREM3 polymorphism correlates closely with the polymorphism that is specific to Dantu a hybrid gene comprising GYPA and GYPB, which encodes a blood antigen known as Dantu (Red blood cell tension protects against severe malaria in the Dantu blood group)." (PMID 33981715, 2021). "In the remaining genomic risk loci, the well-known genes that play role in severe malaria resistance including ATP2B4 (chr1q32), FREM3, GYPE, and GYPB (chr4p31) were replicated and few additional genes were identified." (PMID 34868193, 2021). "Through bioinformatic analysis, we identified extensive variation in glycophorin B (GYPB) transcript levels in individuals from Benin, suggesting selection from malaria pressure." (PMID 28760933, 2017). "GYPB transcript levels vary widely among healthy individuals in a region where malaria is endemic." (PMID 28760933, 2017). "Another notable complex structural variant, called DUP4, creates a GYPB-GYPA fusion gene that alters the surface properties of RBCs and generates a hybrid glycophorin variant, called Dantu, making them less susceptible to P. falciparum invasion and confers a reduced risk of severe malaria." (PMID 40574735, 2025). "However, at present no data indicating a correlation between the GYPB rs6840234 variant and resistance to malaria are available." (PMID 33981715, 2021). "However, the rapid evolution of human glycophorins may have also been driven by P. falciparum, ("evasion hypothesis") as both GYPA and GYPB are receptors of this malaria parasite." (PMID 20682051, 2010). "To determine if this GYPB transcript level variation translated to receptor expression variation, we measured the levels of GPB, as well as GPA, GPC, and other blood group receptors, in healthy donors in Senegal, where malaria is endemic, over two consecutive years." (PMID 28760933, 2017).
cerebral infarction (1 paper, 2022). An ischemic condition of the brain, producing a persistent focal neurological deficit in the area of distribution of the cerebral arteries. "We found that GYPB was highly expressed in AF patients with cerebral infarction, compared to AF patients alone." (PMID 35138035, 2022).
COVID-19 (1 paper, 2021). A disease caused by infection with severe acute respiratory syndrome coronavirus 2. "Finally, for the genes GYPB and FCGR2A, further investigations are needed to confirm an association with COVID-19 along with molecular studies to shed light on the mechanisms responsible for higher/lower incidence of SARS-CoV-2 infections." (PMID 33981715, 2021).
virus infection (1 paper, 2021). "GYPB rs6840234 decreases the expression of both glycophorin B and FREM3, and how this effect can protect against virus infection remains to be elucidated." (PMID 33981715, 2021).
infection (2 papers, 2011 to 2019). The state of being infected such as from the introduction of a foreign agent such as serum, vaccine, antigenic substance or organism. "GYPB*S is associated with host susceptibility to infection with P. falciparum; GYPB*S/GYPB*S and GYPB*S/GYPB*s were significantly more prevalent in the in the P. falciparum infected individuals than in the controls (69.87% vs. 49.75%; P<0.02)." (PMID 21283638, 2011). "Our study aimed to establish whether variation in the GYPB*S/s alleles influences susceptibility to infection with P. falciparum in the admixed population of Brazil." (PMID 21283638, 2011).
GYPB also shares sentences with these, for which no sentence is quoted: atrial fibrillation (1 paper); hemochromatosis (1); Hypertension (1); Obesity (1); Parkinson’s (1); sickle cell disease (1); Stroke (1); trisomy 21 (1).